MIR3667HG (MIR3667 host gene)
Synonyms: C22orf34
Gene: Long non-coding RNA gene on chromosome 22 (49,414,523 to 49,658,432, reverse strand). Ensembl gene ENSG00000188511.
Diseases named in the same sentence as MIR3667HG in open-access papers:
MIR3667HG is named in the same sentence as 8 diseases in open-access papers, as found by Europe PMC text mining. Sharing a sentence is not in itself a finding about the gene and the disease.
MIR3667HG shares sentences with these, for which no sentence is quoted: tumor (3 papers); bladder carcinoma (1); cancer (1); gastric cancer (1); hepatocellular carcinoma (1); melanoma (1); myocardial infarction (1); renal carcinoma (1).